PER1 (period circadian regulator 1)
Diseases named in the same sentence as PER1 in open-access papers (continued):
Sharing a sentence is not in itself a finding about the gene and the disease.
Anxiety (17 papers, 2015 to 2025). Intense feelings of nervousness, tension, or panic often arise in response to interpersonal stresses. "In this same study, loss of the circadian gene Per1 was shown to increase depressive- and anxiety-like behavior in mice." (PMID 35126036, 2021). "Inhibition of Per1/Per2 expression in the nucleus accumbens (NAc) of wild-type mice also produces anxiety-like behavior, suggesting a causal role for these core clock components in the NAc for regulating anxiety." (PMID 32066704, 2020). "ClockΔ19 mice show decreased anxiety-like behavior, whereas loss of functional PER1 and PER2 has the opposite effect." (PMID 29230328, 2017). "As we saw in our experiment, dLAN causes anxiety behavior and reduces the expression of PER1." (PMID 34573555, 2021). "Clock-mutant mice showed reduced anxiety, whereas animals with decreased PER1 and PER2 expression were more likely to exhibit fearful behavior." (PMID 39408776, 2024). "Considering the role of somatostatin (SST) in the amygdala in the circadian modulation of anxiety, we assessed Per1 and c-FOS expression in SST neurons in the MeA." (PMID 38952923, 2024). "Chronic social defeat stress induced mPer1 and mPer2 expression in the NAc and elective Per1 and Per2 knockdown in the NAc increased anxiety-like behavior as seen in the mPer1/mPer2 mutant animals." (PMID 37441675, 2023). "The presence of both melatonin receptors and the Per1 protein in the inferior olivary nucleus can indicate a functional role not only in physiological, as in sleep, anxiety, and circadian rhythm, but also a chronobiotic role in motor control mechanisms." (PMID 36605547, 2022). "A similar result was found in global Per2 knockout mice assessed in the open field, whereas assessment of genome-wide deletions of either Per1 or Per2 in the elevated plus-maze revealed mixed outcomes on anxiety-like behavior." (PMID 35755440, 2022). "Concomitant knockdown of per1 and per2 in the nucleus accumbens of mice also elevates anxiety-like behavior." (PMID 34842772, 2021). "The study was carried out on the animals for three weeks in dim light at night (dLAN) and complete darkness (DD), monitoring the body weight, daily food intake, anxiety-like behavior, and expression of the period (PER1) gene." (PMID 34573555, 2021). "Although when crossed with mice that lack functional Per1, the double mutant mice showed increased anxiety-like behavior, indicating that disrupting both genes is necessary to perturb anxiety-like behavior." (PMID 29230328, 2017). "This phenotype is similar to that of ClockΔ19 mutant mice, which exhibit reduced anxiety-like behaviors and is the opposite of the Per1−/−/Per2−/− double mutant, which exhibit increased anxiety-like behavior." (PMID 29163035, 2017). "In addition, scientists have found that melatonin receptor agonists relieved patients’ depression and anxiety with decreased Per1, Per2, Cry1, Cry2 and Nr1d1 expression." (PMID 36699021, 2022). "In the present study on mice, following three weeks of housing in dim light at night (dLAN; 5lux) and complete darkness (DD; 0lux), we monitored the effect on body weight, daily food intake, anxiety-like behavior by employing the open field test, and expression of the period (PER1) gene." (PMID 34573555, 2021). "In order to challenge the hypothesis that expression of Per1 in the LHb plays an important role in the regulation of despair based and anxiety-related behavior, we deleted Per1 in neurons of the LHb." (PMID 34237069, 2021). "Therefore, in this study, we undertook three weeks of exposure of mice to dLAN and DD to assess anxiety and altered homeostasis, together with the expressional change of the sleep gene PER1." (PMID 34573555, 2021). "The introduction of curcumin increases PER1 expression and improves stress and anxiety conditions." (PMID 34573555, 2021).
Anxiety (continued). "Further supporting a role for Per genes outside of the SCN in the modulation of mood and anxiety-like behaviors, Spencer and colleagues showed that knocking down both Per1 and Per2 in the nucleus accumbens was sufficient to increase anxiety-like behavior in mice." (PMID 29230328, 2017). "Hence, Per1 is likely involved in the despair and anxiety aspects of mood-related behaviors." (PMID 34237069, 2021). "Another melatonin receptor agonist, ramelteon, improves depression and anxiety symptoms by increasing BDNF levels and targeting clock genes (e.g., Per1 and Per2)." (PMID 36699021, 2022). "Because Per1 and Per2 negatively regulate NPAS2/BMAL1 transcription, this further supports a role for NPAS2 in the regulation of anxiety-like behaviors." (PMID 29163035, 2017). "These clusters particularly involved genes related to regulatory subunits of cAMP-dependent protein kinases, such as PRKAR2A, cAMP-responsive element-binding pathway, circadian rhythms, such as CLOCK, ARNT1, CRY2, PER1, and PER2, and anxiety and depression, such as NOTCH1, NOTCH2 and ANK2." (PMID 41157308, 2025). "In contrast, mice lacking both Per1 and Per2 display elevated anxiety-like behavior, whereas mice lack either Per1 or Per2 do not have altered anxiety-like responses." (PMID 32066704, 2020). "Mice lacking both Per1 and Per2 showed robust increase in anxiety and depression phenotypes." (PMID 37441675, 2023). "In another study involving animals, mice lacking PER1 and PER2 expression exhibited increased anxiety compared to wild-type controls." (PMID 39408776, 2024).
diabetes (16 papers, 2014 to 2025). "In the present study, B12 modulated several core clock genes (Bmal1, Cry1, Cry2, Per1, Per3), while other genes were primarily affected by diabetes (Bhlhe40, Hif3a, and Nr1d1)." (PMID 41463345, 2025). "More importantly, the mRNA levels of BMAL1 and PER1 genes were found to be significantly lower in the diabetes group with poor sleep quality compared to that with good sleep quality." (PMID 28352282, 2017). "Diabetes remission following VSG in GK rats is associated with increased expression of Dbp, Per1, Per2 and Per3 and decreased expression of Naps2, Arntl/Bmal1 and Clock, which fit the known feedback loop transcriptional regulation of these genes in the pathway." (PMID 41360887, 2025). "We previously reported that elevated Per1 expression caused by streptozotocin (STZ) plays an important role in the aggravation of diabetes, and that Per1 expression in the back skin hairs responded to blood glucose changes in very early stages of diabetes." (PMID 36831320, 2023). "PER1, which has been verified to participate in the regulation of circadian rhythm, target by the yangyinyiqi component of SHENQI compound to mediates diabetes." (PMID 30521536, 2018). "In our study, the transcript levels of BMAL1, PER1, and PER3 were also significantly lower in the diabetes groups compared to the normal control group." (PMID 28352282, 2017). "Furthermore, mRNA expression of circadian clock genes such as PER1 and BMAL1 is dampened in peripheral leucocytes of diabetes subjects with poor sleep quality." (PMID 28352282, 2017). "A list of 15 known clock genes from the primary (Arntl, Clock, Npas2, Per1, Per2, Per3, Cry1, Cry2), secondary (Nrd1d1, Nr1d2, Rora, Rorb, Rorc), and accessory TTFL loops (Nfil3, Dbp) were selected to investigate the effect of diabetes on their rhythmic expression." (PMID 38039846, 2024). "The mRNA expression of BMAL1, PER1, PER2, and PER3 in leukocytes was observed to be lower in non-diabetic individuals, as compared to those with diabetes." (PMID 37475884, 2023).
ocular melanoma (16 papers, 2021 to 2025). A melanoma that arises from the structures of the eye or ocular adnexa.
depression (15 papers, 2009 to 2025). "In the present study, we investigated the effects of PER1 (rs7221412) gene polymorphisms on the associations between WM integrity and depression level (measured by BDI) using TBSS analysis." (PMID 36440417, 2022). "Compared with homozygous form of PER1 gene (AA), more individuals with risk allele G of PER1 gene (AG) were in depression state with BDI cutoff of 14 (χ2 = 7.37, uncorrected p = 0.007)." (PMID 36440417, 2022). "We hypothesize that the PER1 gene polymorphisms will modulate the relationship between depression level and WM microstructural integrity in emotion-related brain regions." (PMID 36440417, 2022). "Our findings suggested that the PER1 genotypes and emotion-related WM microstructure may provide more effective measures of depression risk at an early phase." (PMID 36440417, 2022). "Finally, RORA rs1568717 and PER1 rs885747 showed suggestive evidence for association with depression and early morning awakening (P = 0.026, OR = 1.60, and P = 0.040, OR = 0.66, respectively)." (PMID 20174623, 2010). "Therefore, PER1 gene polymorphisms and WM microstructure may be promising indictors for early identification of depression risk." (PMID 36440417, 2022). "Therefore, combined our results, these findings suggested that PER1 gene may play a role in depression risk." (PMID 36440417, 2022). "In conclusion, decreased FA in several WM tracts were shown in PER1 (rs7221412) AG group compared with the AA group, and PER1 genotype had an interaction effect on the associations between the WM microstructural integrity in emotion-related WM tracts and depression level." (PMID 36440417, 2022). "Many studies indicate the involvement of Per1 and Per2 in patients with depression and bipolar disorder, with increasing reports highlighting the role of Per2 in BD." (PMID 40011706, 2025). "Among these, morning expression of the PER1 gene emerged as an independent predictor of depression severity, even after adjusting for insomnia and chronotype-related variables." (PMID 41425214, 2025). "In a mouse model of depression, Period1(Per1) levels are positively correlated with the severity of depression." (PMID 36699021, 2022). "In order to explore the effect of PER1 on the relationship between WM characteristics and depression level, we analyzed the interaction effects of genotype × BDI on WM characteristics." (PMID 36440417, 2022). "In other words, 24% (6/25) subjects with the PER1 heterozygote were in depression state among the 1/3 population and 6/8 of people with depression were the AG genotype." (PMID 36440417, 2022). "Findings from the targeted examination of clock genes revealed several significant associations with depression (NR1D1 and PER1) and BIP-I (ARNTL, CRY2, RORB) underlining the close relationship with mood disorders." (PMID 36131119, 2022). "In the targeted examination of circadian genes, significant associations (padj < 0.05) of depression with NR1D1 (Z = 4.23, p = 1.16 × 10–5) and PER1 (Z = 2.94, p = 0.002) were observed." (PMID 36131119, 2022). "We found that more subjects with PER1 heterozygotes were in depression state (BDI ≥ 14) than AA group, and showed poorer WM integrity in CC, internal capsule, corona radiata and fornix." (PMID 36440417, 2022). "Interestingly, the antipsychotic medication quetiapine, used to treat major depression, has also been shown to increase PER1 expression in the amygdala." (PMID 39408776, 2024). "However, only 4% (2/52) of subjects were in depression state among the PER1 A homozygote population and 2/8 of people with depression were in the AA group." (PMID 36440417, 2022). "Hence lack of phase advance and increased immobility in the FST of Per1 knock-out mice inversely correlated with the observation in humans in which advance of sleep phase had a positive effect on depression." (PMID 34237069, 2021). "Interestingly, the profiles of Per1 and Rev-erbα were advanced in patients in the manic phase compared with those in the depression phase." (PMID 34237069, 2021).
depression (continued). "In females with depression accompanied by fatigue (D+FAT+), we found some evidence of interaction between TIMELESS rs7486220 and PER1 rs3027188 (P = 0.008, OR = 0.45)." (PMID 20174623, 2010).
melanoma (15 papers, 2016 to 2025). A malignant, usually aggressive tumor composed of atypical, neoplastic melanocytes. "Genetic disruption of the clock through per1/2−/− loss in mice enhances immune response to melanoma tumors, which further contributes to tumor treatment efficacy." (PMID 29581861, 2018). "Consistently silencing PER1 in melanoma cells promotes tumor proliferation and development in an in vitro experiment, while overexpression of PER1 enhances the apoptosis of squamous cell carcinoma." (PMID 34069297, 2021). "We performed a separate experiment aimed to identify immune response to melanoma tumors in the wild-type and Per1/2−/− mice." (PMID 29581861, 2018). "After observing that the Per1/2−/− mice had better cisplatin treatment efficacy against melanoma tumors with both low and high doses, we sought to identify underlying contributing factors." (PMID 29581861, 2018). "Collectively, the more robust CD4+ and CD8+ T cell populations and infiltration to tumor sites of the Per1/2−/− mice suggests that clock-regulated immune function plays an important role in sensitizing melanoma tumors to cisplatin treatment." (PMID 29581861, 2018). "We injected B16F10 melanoma tumor cells (2 × 105 cells/mouse) subcutaneously into the lower right flank region of wild-type and Per1/2−/− mice." (PMID 29581861, 2018). "It was found that Per1, Per2, Clock, and Cry1 expression was reduced in the melanoma biopsies as compared to adjacent normal skin in the majority of melanoma patients." (PMID 27128901, 2016). "The implicated mechanism involves the recognition of m6A-modified PER1 by the protein YTHDF2, which may accelerate melanoma progression." (PMID 40191195, 2025). "Additionally, PER1 and PER2 in the TME induced chemoresistance and immunosuppression in a melanoma mouse model." (PMID 37524704, 2023). "By comparing biopsies from human melanoma to non-tumorous samples, they were able to show that the expression of Per1, Per2, Clock and Cry1 clock genes and corresponding protein levels in the nucleus were reduced by 30%–60% in melanoma versus normal skin." (PMID 27231897, 2016). "Similarly, the number of PER1 immunopositive cells in melanoma as compared to nevus biopsies was not significant highlighting that Per expression is not inherently a feature of malignancy." (PMID 27128901, 2016). "However, the lack of Per1 bioluminescence induction may be related to an already upregulated cAMP signaling, which is a common feature known in melanoma cells." (PMID 35562405, 2022).
gastric cancer (13 papers, 2015 to 2025). A primary or metastatic malignant neoplasm involving the stomach. "The downregulation of PER1 is associated with poor prognosis: patients with high PER1 expression in gastric cancer exhibit prolonged survival (P = 0.0028)." (PMID 41451215, 2025). "Disturbance of the circadian clock has been linked to cancer; specifically, deregulation of Per1 and Per2 have been connected to gastric cancer and suggested as prognostic markers." (PMID 25853007, 2015). "In trastuzumab-resistant gastric cancer cells, PER1 complexes with PPAR-γ to promote upregulation of hexokinase 2 (HK2), thereby enhancing glycolytic activity." (PMID 41451215, 2025). "This suggests that targeting PER1 could be a promising strategy for overcoming trastuzumab resistance in gastric cancer." (PMID 40243466, 2025). "In addition, the circadian rhythm of the PER1/HK2 axis was shown to be significantly correlated with trastuzumab resistance in gastric cancer." (PMID 40415238, 2025). "Besides, it was shown that trastuzumab-resistant gastric cancer cells displayed PPARγ- and PER1-controlled circadian fluctuations in their glycolytic activity." (PMID 35890319, 2022). "Functionally, the TPTEP1/miR-548d-3p/KLF9/PER1 axis reduces gastric cancer cell migration and invasion, with KLF9 serving as the critical regulatory node that translates the long non-coding RNA TPTEP1’s tumor-suppressive effects into PER1-mediated anti-metastatic activity." (PMID 40860800, 2025). "PER1 and PER2 genes are currently considered to be true tumor suppressor genes, as decreased expression of either (or both) has been reported in several types of human cancers and has been shown to be an independent predictor of poor prognosis in patients with gastric cancer." (PMID 31409384, 2019).